ICOS (inducible T cell costimulator)
Diseases named in the same sentence as ICOS in open-access papers (continued):
Sharing a sentence is not in itself a finding about the gene and the disease.
cancer (continued). "Although the most advanced knowledge has been generated around the therapies targeting PD-1/PDL-1 or CTLA-4, there are multiple other important pathways that may impact the immune response to cancer involving many genes, in particular LAG-3, TLR-4, VISTA, TIM-3, TIGIT, ICOS, OX40, and GITR5." (PMID 33911192, 2021). "Additionally, regarding ICOS+ FOXP3+ Tregs, an increased prevalence in carcinoma was not only associated with the absolute number but also with the percentage of FOXP3+ cells." (PMID 27725696, 2016). "This suggests that triggering ICOSL/ICOS pathway may not be the most optimal option for cancer treatment." (PMID 23450201, 2013). "Consequently, mutein should be advantageous in the treatment of those cancer diseases where the Treg expansion is relevant; in these settings, we expect better efficacy and lower percentages of non-responder patients due to lower levels of ICOS+Treg proliferation." (PMID 36059465, 2022). "As far as other co-stimulation, while ICOS expression has been seen in human melanoma TIL for cytotoxic CD4+ T cells, this is not universally seen across the other cancer/non-cancer studies." (PMID 34910940, 2021). "For the most common cancer types in the current study, ICOS and ICOSL high were co-expressed in 2.0% (colorectal) to 14.6% (pancreatic), whereas ICOSL high was co-expressed with ICOS not high in 29.1% (pancreatic) to 46.4% (colorectal) of patients." (PMID 40297627, 2025).
infection (83 papers, 2010 to 2026). The state of being infected such as from the introduction of a foreign agent such as serum, vaccine, antigenic substance or organism. "The treatment of infection was associated with a decrease in Treg level and a switch in their phenotype, namely, a decreased expression of ICOS and of naïve Treg and a systemic IL-6 and IL-4 inflammatory response." (PMID 34111180, 2021). "Increased expression of the survival factor Bcl-2 following antibody-mediated blockade of ICOS in the chronic phase of infection has previously been implicated as a mechanism supporting increased survival of effector T cell populations in the inflamed brain." (PMID 31978191, 2020). "Since the generation of ICOS deficient T effector cells with a Tfh cell phenotype was limited after transfer and infection, we anticipated that the corresponding humoral response in the tcrb-/- recipient mice would be diminished." (PMID 32348365, 2020). "Previous work has implicated ICOS-ICOSL interactions in Tfh cell differentiation after primary immunization or infection." (PMID 32348365, 2020). "In humans, ICOS deficiency results in severe impairment of germinal center formation and inability to mount antibody responses against infection or vaccination." (PMID 30405612, 2018). "Concomitantly, regulatory T cell (Treg) frequency was significantly reduced in ICOS-deficient mice in this infection model." (PMID 27559335, 2016). "Upon infection, the increase in the expression of surface markers such as GITR, ICOS and PD-1, which have been associated to the suppressive activity of Tregs, is consistent with findings from others, such as in the infection with RSV or M. tuberculosis." (PMID 26512987, 2015). "Consistent with our previous findings made with ICOSL-KO mice, ICOS-KO mice developed more drastic weight loss compared to WT mice during the early phase of infection." (PMID 23285133, 2012). "When ICOS deficient mice were infected with P. chabaudi, primary parasitemia was significantly lower compared to control mice with a corresponding higher frequency of Th1 cells during this early phase of infection." (PMID 30631323, 2018). "During cutaneous Leishmania mexicana infection, for example, researchers observed a slight reduction in IFN-γ and IL-4 production in Icos−/− mice at week 6 post-infection, while the production of both cytokines was substantially reduced in ICOS-deficient mice by week 12 post-infection." (PMID 27559335, 2016). "Additionally, ICOS has been directly linked with Treg induction during infection." (PMID 27559335, 2016). "Therefore, to determine whether ICOS deficiency has a similar impact on Foxp3+ Treg cells at the infection site, we compared Foxp3+ Treg-cell responses in the LP of the small intestine of H. polygyrus-infected WT and ICOS−/− mice." (PMID 23319295, 2013). "This revealed a decrease in CD8+ T cells coexpressing various combinations of activation markers CD38, Ox40, and ICOS following breakthrough infection, but again only in the context of pregnancy." (PMID 40693463, 2025). "While CD103+ cells also showed increased CD69 and ICOS expression post-infection, the changes were less pronounced than in CD103− cells." (PMID 41459157, 2025). "CD4+ T cells with high coexpression of the PD-1 and ICOS activation markers increased in frequency from approximately 0.1% at baseline to a peak of approximately 1%–2% between weeks 8 and 21 after infection." (PMID 40956619, 2025). "Infection with M. benedeni led to a significant increase in ICOS expression in all intestinal segments: the ileum showed the highest increase in expression level (P < 0.05), followed by the jejunum (P < 0.05) and duodenum (P < 0.05)." (PMID 40316996, 2025). "At the 8th week post-infection, in undernutrition 65% + infection group, PD-1, PD-L1, Bax and ICOS were upregulated and CD3+CD4+ and CD3+CD8+ T cell proportions were decreased, while the level of serum IL-10 was increased and IL-12 p70 was decreased." (PMID 38185681, 2024).
infection (continued). "It is most likely that the roles of ICOS in the protective activities of CD8+ T cells against T. gondii differ depending on the genetic resistance and susceptibility of the hosts to the infection." (PMID 39682747, 2024). "In undernutrition 65% + infection group, PD-1 (P = 0.0364), PD-L1 (P = 0.0481) and Bax (P = 0.0394) were conversely upregulated, and ICOS (P = 0.0274), TLR2 (P = 0.0097) and TLR4 (P = 0.0361) were also upregulated." (PMID 38185681, 2024). "The frequency of ICOS+Blimp1+ P14 CD8+ T cells was significantly higher on CD8+ T cells in +Ag skin on day 7 post infection." (PMID 37402742, 2023). "Nonetheless, largely congruent with data from protein immunization experiments, this infection model confirmed the critical role of ICOS in efficient Tfr generation." (PMID 36754569, 2023). "We approached this, by inhibiting ICOSL:ICOS interaction during the acute MCMVΔm138 infection via the administration of a blocking anti-ICOSL antibody." (PMID 33459589, 2021). "In this study, we demonstrate that the ligand for the co-stimulatory molecule ICOS is dramatically diminished from the surface of APCs during infection by different herpesviruses." (PMID 33459589, 2021). "Together these findings verify that ICOS signaling in memory T cells plays an integral role in promoting T cell effector responses during secondary infection with P. c. chabaudi AS." (PMID 32348365, 2020). "One such signal, ICOS, has previously been shown to play a costimulatory role early in the infection during T cell priming." (PMID 31978191, 2020). "During infection with T. gondii, ICOS promotes early T cell responses, while in the chronic stage of infection ICOS plays a regulatory role by limiting T cell responses in the brain." (PMID 31978191, 2020). "Here, we describe the importance of the co-stimulatory molecule ICOS during secondary infection with the rodent parasite Plasmodium chabaudi chabaudi AS." (PMID 32348365, 2020). "Nevertheless, Ag-expT-bet+ Th1 cells on day 15 of infection exhibited reduced proliferation (Ki67+), function (IFN-γ+), and activation (ICOS+) compared with Ag-expT-bet+ Th1 cells on day 5 of infection." (PMID 32817333, 2020). "In the chronic stage of infection, however, ICOS takes on a regulatory role by limiting effector T cells in the brain." (PMID 31978191, 2020). "Based on these previous reports, it was possible that ICOS KO and ICOS YF mice fail to produce adequate parasite-specific antibody during infection, therefore leading to increased parasite burdens in the brains of chronically infected animals." (PMID 31978191, 2020). "Ag-expCD4+ T cell effector function continued to deteriorate between days 9 and 15 of infection, with cells on day 15 of infection, expressing low levels of Ki67, ICOS, and CD25 and producing very low levels of TNF, IFN-γ, IL-2, and IL-10." (PMID 32817333, 2020). "ICOS (inducible T cell costimulator) is one of a multitude of costimulatory molecules that has been shown to be important for optimal immune response to infections." (PMID 31978191, 2020). "Whereas the role of ICOS in infection is well established in T cells data on NK cell-mediated responses are lacking." (PMID 31283790, 2019). "Upon infection there were fewer NK cells in the spleen, but more in the site of inoculation, the peritoneum of both WT and ICOS-KO mice." (PMID 31283790, 2019). "The role of ICOS in parasite growth and pathology, thus, led us to further characterize its expression during PbA infection." (PMID 29892278, 2018). "On day 3 and day 6 of PbA infection, mice were sacrificed and their spleens analyzed for surface markers to identify ICOS expression on CD4+, CD8+, NK, NKT, and B cells by flow cytometry." (PMID 29892278, 2018). "A significant increase in mean fluorescent intensity for ICOS on CD4+ and CD8+ T cells suggested that expression of ICOS at protein level per cell was also higher on day 6 of PbA infection." (PMID 29892278, 2018).
infection (continued). "Depending on the nature of antigen and chronicity of infection, ICOS signaling mediates differential effector CD4+ T cell response." (PMID 29892278, 2018). "In an acute infection model, ICOS is required for the early CXCR5+Bcl6+ TFH differentiation of antigen-specific T cells as early as 3 days following infection with lymphocytic choriomeningitis virus (LCMV)." (PMID 30405612, 2018). "Our results showed that the proportion of ICOS+ Tfh cells and PD-1+ Tfh cells were also increased much more quickly during the first seven weeks post-infection and kept a higher level subsequently." (PMID 29192177, 2017). "Although ICOS can modulate Th1/Th2 differentiation during infection, early observations connected ICOS co-stimulation with Ab production." (PMID 27559335, 2016). "As a whole, ICOS has been shown to regulate various T helper cell subsets during different infection scenarios, largely by promoting or inhibiting Th1 and Th2 immune responses." (PMID 27559335, 2016). "Nevertheless, the studies presented here indicate that ICOS co-stimulation plays an important role in either enhancing or regulating Th cell expansion and/or differentiation after infection." (PMID 27559335, 2016). "chabaudi AS infection, although Icos−/− mice produced fewer IgM− MBCs at week 9 post-infection relative to wild-type mice, class-switched MBC production was not fully abrogated in the absence of ICOS signaling." (PMID 27559335, 2016). "Summary of Th impact and disease outcome in various infection models when ICOS signaling is disrupted." (PMID 27559335, 2016). "In contrast, the WT mice showed a comparatively considerable increase in ICOS expression after infection." (PMID 25590646, 2015). "The expression of PB1-F2 during the infection exacerbates the T cell activation through the ICOS signaling pathway." (PMID 23469251, 2013). "Infection of ICOS−/− mice with Heligmosomoides polygyrus or Schistosoma mansoni led to a reduced expansion and maintenance of Foxp3+ Treg cells." (PMID 23319295, 2013). "In contrast, BrdU uptake by CD4+Foxp3− Teff cells at day 7 of infection was severely diminished in ICOS−/− mice." (PMID 23319295, 2013). "This enhancement of Type 2 immunity at the infection site sharply contrasted with the mesenteric LN (MLN), where ICOS deficiency led to weakened Type 2 responses." (PMID 23319295, 2013). "Similar to the CD4+Foxp3+ Treg-cell population, ICOS−/− mice had significantly reduced numbers of CD4+Foxp3− Teff cells during infections with both H. polygyrus and S. mansoni." (PMID 23319295, 2013). "Given that ICOS was dispensable for Foxp3+ Treg-cell proliferation during infection, we asked if the defective Foxp3+ Treg-cell responses evident in ICOS−/− mice were due to impaired survival." (PMID 23319295, 2013). "In infections with parasitic helminths, ICOS is important for the development of Th2 and Ab responses towards the nematodes Nippostrongylus brasiliensis, Trichuris muris, Trichinella spiralis and Brugia malayi." (PMID 23319295, 2013). "This intermediate phenotype of ICOS-YF mice was reflected by the bacterial burden in the lung (14 days post-infection): it was 10-fold higher than that of WT mice but 10-fold lower than that of ICOS-KO mice." (PMID 23285133, 2012). "After challenge with PR8 virus, wild-type mice lost little weight, but ICOS−/− mice lost nearly as much weight after secondary infection as they had during primary infection with PR8." (PMID 21364749, 2011). "Similarly, ICOS can also play a crucial role in anti-parasite infection immunity by regulating the immune response of Th cells." (PMID 40316996, 2025). "Likewise, CD69+CD4+lo T cell levels (p<0.01) PD-1+CD4+lo T cell levels and (p<0.001) were significantly higher in all infected groups whereas the levels of ICOS+CD4+lo T cells were only significantly higher in chronic HBV (p<0.01) infection." (PMID 37163092, 2023).
infection (continued). "At these corresponding time points during infection, splenic 4° effector OT‐I cells during a fourth infection exhibited significantly reduced activation and function, including lower ICOS and GrB, compared with 2° effector OT‐I cells during secondary infection." (PMID 34407221, 2021). "Rather, the increased number of effector T cells correlated with increased expression of CD25 on the surface of effector CD4+ and CD8+ T cells in the brain, which is consistent with previously published results examining the effects of ICOS blockade only in the chronic phase of infection." (PMID 31978191, 2020). "However, the infection induced expression of activation and co-stimulatory molecules, ICOS and CD40L, on CD4+ T cells, known to be crucial for T-B interactions providing help for B cell activation, maturation and antibody production." (PMID 28700710, 2017). "However, the regulatory function of ICOS is not limited to Treg cell induction and IL-10 production, as Icos−/− mice display an enhanced Th1 response after infection with P. c." (PMID 27559335, 2016). "However, as importantly, we found that ICOS also plays a role in controlling IL-10 production by CD4+ YFP+ T cells during infection." (PMID 26459508, 2016). "Despite normal lesion formation, however, tissue damage was less severe in Icos−/− mice at week 12 post-infection compared with wild-type mice, suggesting that, in the case of chronic L. mexicana infection, ICOS signaling served to enhance immune-mediated pathology." (PMID 27559335, 2016). "chabaudi AS-infected Icos−/− mice exhibited a profound defect in parasite-specific IgG affinity maturation at weeks 3 and 9 post-infection, suggesting that affinity maturation during murine Plasmodium infection is critically dependent on continuous ICOS signaling." (PMID 27559335, 2016). "Although certain aspects of the GC response may be more or less reliant on ICOS signaling depending upon the immunization or infection model in question, these data provide evidence of dysregulated GCs in the absence of ICOS signaling." (PMID 27559335, 2016). "In a similar fashion, although defective Th2 immunity was observed during acute Trichuris muris infection, Icos−/− mice produced more IL-13 and IL-5 at day 35 post-infection compared with wild-type mice, suggesting that Th2 immunity was slower to develop in the absence of ICOS." (PMID 27559335, 2016). "We consequently questioned whether ICOS plays a role in the subsequent stabilization or maintenance of IL-10 expression by CD4+ T cells during infection potentially downstream of the IL-27R-dependent induction of IL-10 expression." (PMID 26459508, 2016). "Although ICOS is seemingly capable of alternatively promoting or repressing Th1 responses under different infection conditions, these divergent phenotypes may in part be explained by ICOS-dependent Treg induction." (PMID 27559335, 2016). "Likewise, in the context of Trichinella spiralis and Leishmania major infection, treatment of wild-type mice with anti-ICOS or anti-ICOSL Abs served to diminish the Th2 immune response, reducing the production of IL-4, IL-5, and IgE." (PMID 27559335, 2016). "Thus, it is notable that anti-ICOS administration from day 3 of infection, after initial CD4+ T cell priming and differentiation events, led to impaired IL-10 production by parasite-specific CD4+ YFP+ T cells." (PMID 26459508, 2016). "In support of this hypothesis, blockade of ICOS from day 3 of infection, which is after CD4+ T cell priming, significantly abrogated the expression of IL-10 by parasite-specific CD4+ T cells in all examined organs." (PMID 26459508, 2016). "In all infection models reviewed herein, disruption of ICOS signaling led to poor CD4+ T cell Th2 polarization and diminished IL-4 production, which may or may not have been due to reduced expansion of CD4+ T cells in all cases." (PMID 27559335, 2016).